RNU5E-3P (RNA, U5E small nuclear 3, pseudogene)
Gene: Small nuclear RNA gene on chromosome 4 (48,574,453 to 48,574,520, reverse strand). Ensembl gene ENSG00000251722.
Homologues: Orthologues: chimpanzee U5 (100% identical), rat LOC120095804 (84% identical), pig U5 (82% identical). Paralogues in human: RNU5E-10P (90% identical), RNU5B-6P (87% identical), RNU5E-7P (84% identical), RNU5F-6P (84% identical), RNU5F-7P (84% identical), RNU5B-2P (82% identical), RNU5E-8P (82% identical), RNU5A-4P (81% identical), RNU5E-4P (81% identical), RNU5F-4P (81% identical), RNU5A-5P (79% identical), RNU5A-8P (79% identical), and 13 more.